COL10A1 (collagen type X alpha 1 chain)
Diseases named in the same sentence as COL10A1 in open-access papers (continued):
Sharing a sentence is not in itself a finding about the gene and the disease.
breast carcinoma (continued). "Conversely, age, SBR, basal-like status and triple-negative status were negatively related to COL10A1 level in breast cancer samples compared with normal tissues." (PMID 32043519, 2020). "Conversely, age, the Scarff–Bloom–Richardson (SBR) grade, basal-like status, and triple-negative status were negatively related to COL10A1 level in breast cancer samples compared with normal tissues." (PMID 32043519, 2020). "The third gene, COL10A1, has been widely reported to be a oncogene in multiple cancer types, contribute to vasculature, and also used as biomarker for neo-adjuvant therapy effect prediction indicator in ER+/HER2+ breast cancer." (PMID 28977887, 2017). "By comparing the COL10A1 and LRRC15 expression heat map derived from the UCSC Xena web-based tool, COL10A1 expression was proved to be positively related with LRRC15 transcript level, which was determined among a 50-gene qPCR assay (PAM50) breast cancer subtypes in TCGA database." (PMID 32043519, 2020). "Similarly, for early breast cancer, the best three k-gene discriminators are {GPR109B, PCOLCE2, PCSK5}, {PCSK5+COL10A1, FERMT2+SPINT2, MAOA+IGJ}, {COL1A1+PCSK5+TF, GPX3+COL1A1+SPINT2, GPX3+FAP+TMEM97}, and {RRM2+COL1A1+GPR109B+IGJ, RRM2+COL1A1+GPR109B+IGJ, RRM2+COL1A1+GPR109B+SPINT2}, respectively." (PMID 21060876, 2010).
gastric cancer (35 papers, 2013 to 2025). A primary or metastatic malignant neoplasm involving the stomach. "Logistic regression analysis indicated that high expression of COL10A1 in gastric cancer was largely associated with pathological stage, tumor differentiation, and T classification." (PMID 36246404, 2022). "It has been illustrated by the analysis of logistic regression that COL10A1’s heightened expression in gastric cancer had been essentially linked with pathological stage, tumor differentiation, and T classification." (PMID 33371777, 2021). "The study showed that the abnormally high expression of COL10A1 promotes the proliferation, migration, and invasion of gastric cancer cells and is associated with poor tumor stage, which is consistent with our results." (PMID 33934516, 2021). "It has been displayed by the Univariate and multivariate survival analysis that the upregulated expression of COL10A1 in gastric cancer happened to be the independent risk factor for shorter OS." (PMID 33371777, 2021). "COL10A1 expression was found to be an independent risk factor for gastric cancer." (PMID 41373732, 2025). "High COL10A1 expression had been linked to the poor gastric cancer prognosis." (PMID 33371777, 2021). "The elevation of COL10A1 was linked to few clinic pathological features of gastric cancer." (PMID 33371777, 2021). "Recent multi-omics studies have shown aberrant upregulation of COL10A1 in the tumor stroma of breast, pancreatic, and gastric cancers, where it correlates with lymph node metastasis, hematogenous spread, and poor prognosis." (PMID 40826474, 2025). "In gastric cancer, the SOX9 expression was associated with collagen type X alpha 1 (COL10A1) to promote migration and invasion of tumor cells." (PMID 38275880, 2024). "COL10A1 has been identified as a promoter of gastric cancer invasion and metastasis, primarily through the process of epithelial-to-mesenchymal transition." (PMID 39494300, 2024). "In gastric cancer, COL10A1 expression was also found to be significantly increased compared to non-tumor specimens, and it was significantly associated with tumor T stage and pathological stage." (PMID 38063927, 2023). "COL10A1 promotes the invasion and metastasis of gastric cancer cells, and COL10A1 is regulated by the TGF-β1-SOX9 axis." (PMID 37974070, 2023). "COL10A1 appears to promote the malignant behaviour of gastric cancer cells, making it a potential therapeutic target and biomarker of gastric cancer." (PMID 37974070, 2023). "COL10A1, a member of the collagen family and the main matrix component, is high expressed in gastric cancer compared to the normal tissues and an independent predictor of poor overall survival." (PMID 36400805, 2022). "To summarize, COL10A1 encourages gastric cancer development by controlling several signaling pathways." (PMID 33371777, 2021). "It is worth noting that this study also used bio‐informational methods to reach this conclusion, further demonstrated that the COL10A1 gene played an important role in stomach cancer." (PMID 33934516, 2021). "qRT-PCR technique was used for verification of the COL10A1’s high expression in gastric cancer in contrast to the normal gastric tissues." (PMID 33371777, 2021). "Through the analysis of database of Oncomine, the Cancer Genome Atlas (TCGA) as well as the Gene Expression Omnibus (GEO), in contrast to the tissue of normal gastric, COL10A1 in gastric cancer, had been upregulated." (PMID 33371777, 2021). "Simultaneously, TGFB2, VEGFB, COL10A1, ERG1 and EFNA5 composed risk model is a promising tool for assessment of gastric cancer survival." (PMID 34332586, 2021). "In gastric cancer (GC), COL10A1 was found to possibly act as a potent co-stimulator of TGF-β1-induced EMT, where its expression was vastly elevated during GC development and progression." (PMID 32564237, 2020).
gastric cancer (continued). "For instance, COL10A1 promotes invasion and metastasis in gastric cancer through transcriptional regulation of SOX9 and the involvement of the TGF-β signaling pathway." (PMID 31992202, 2020). "In the present study, we identified and validated the role of COL10A1 in the migration and invasion of gastric cancer cells." (PMID 30154451, 2018). "Notably, matrix-producing CAFs (matCAFs) characteristically express high levels of COL10A1, and knockdown of COL10A1 in breast and gastric cancer mouse models significantly suppresses tumor proliferation and metastasis." (PMID 40826474, 2025). "Furthermore, we identified two matCAF cell lines from gastric cancer patient tissues, specifically expressing COL10A1." (PMID 38148640, 2023). "Similarly, high levels of COL10A1 have been observed in gastric cancer, representing a key independent predictor of poor outcomes, probably because of COL10A1-mediated upregulation of lymphoid enhancer-binding factor 1 and Wnt2." (PMID 36765749, 2023). "Elevated COL10A1 levels were associated with an advanced tumor stage and with poor survival in gastric cancer patients, whereas in colon cancer, COL10A1 could be used to detect both adenoma lesions and invasive cancer." (PMID 36293285, 2022). "Finally, we established risk model based on key pathways ligands TGFB2, VEGFB, COL10A1, AREG and EFNA5 to predict gastric cancer survival." (PMID 34332586, 2021). "COL10A1 from cancer-associated fibroblasts promotes LUSC cell proliferation and inhibits oxidative stress-induced apoptosis, and may also serve as a potential biomarker for gastric cancer progression and prognosis." (PMID 36967783, 2023). "For example, miR-26a-5p reduces COL10A1 expression by binding to the 3’-UTR of COL10A1, thereby inhibiting the proliferation, migration and invasive ability of gastric cancer cells." (PMID 39198393, 2024). "In the gastric cancer (STAD) model, in vivo imaging and bioluminescence analysis showed that matCAF with COL10A1 knockdown substantially reduced STAD's abdominal metastasis capacity." (PMID 38148640, 2023). "COL10A1 also promotes the malignant progression of gastric cancer and may be a therapeutic target and predictive biomarker in GC patients." (PMID 37974070, 2023). "The Cox proportional hazard model of COL8A1, COL10A1, CTHRC1, and FAP and six tumor-infiltrating immune cells in gastric cancer (TIMER)." (PMID 35910202, 2022). "For example, collagen type I alpha 2 chain (COL1A2) was suggested to be a novel biomarker to enhance the clinical prediction of gastric cancer, and collagen type X alpha 1 (COL10A1) might be a key independent predictor of poor over survival of GC patients." (PMID 34506251, 2021). "The previous study elucidated the mechanistic link between COL10A1 and the TGF-β1–SOX9 axis in gastric cancer progression." (PMID 32043519, 2020). "In hepatocellular carcinoma (HCC) and gastric cancer, miR-26a-5p expression has been reported to inhibit proliferation, migration, and invasion by downregulating oncogenic signaling pathways (e.g., the HGF-Met and COL10A1 pathways)." (PMID 39288140, 2024). "COL10A1 was proved to promote metastasis by inducing epithelial-mesenchymal transition in gastric cancer 31 and the over-expression of COL10A1 had a negative effect on the prognosis of patients in colorectal cancer." (PMID 33753985, 2021). "The gastric cancer tissues expressed higher levels of COL10A1 compared with the corresponding non-cancerous region using fluoroscopy and immunohistochemistry methods." (PMID 30154451, 2018). "Although no studies have yet reported on COL10A1, ADA, or LHFP and cancer survival, CTSB and MMP9 have both been previously associated with survival in gastric cancer, while ESRRG expression has been associated with survival in prostate cancer." (PMID 23717493, 2013).
gastric cancer (continued). "Collagen type X alpha 1 (COL10A1) activates the WNT2-mediated Wnt pathway and promotes the development of gastric cancer, and the vast majority of patients with high expression of WNT2 have cancer in TNM Stage III or IV with lymph node metastasis, it may be a marker for patients with advanced GC." (PMID 38952556, 2024). "However, COL10A1 expression and prognosis relationship remains unclear in gastric cancer (GC)." (PMID 33371777, 2021).
colorectal cancer (18 papers, 2014 to 2025). A primary or metastatic malignant neoplasm that affects the colon or rectum. "The published literature has reported that in colorectal cancer, COL10A1 expression is associated with tumor progression and metastasis, and high expression of COL10A1 has been linked to poor overall survival and disease-free survival (DFS) in colorectal cancer patients." (PMID 41373732, 2025). "Similarly, in colorectal cancer, a COL10A1-positive fibroblast subpopulation (COL10A1+Fib) has been associated with tumor progression and poor prognosis in patients." (PMID 41303526, 2025). "High COL10A1 expression could cause tumor progression and independently predicted the OS of patients suffering colorectal cancer." (PMID 36276283, 2022). "At the protein level, examination of 35 paired colorectal cancer clinical specimens showed that COL10A1 was over-expressed in the tumour group in both paired and unpaired analyses, and its expression increased with advancing stage." (PMID 40826474, 2025). "Analyzing the transcriptome data of TCGA colorectal cancer patients, we found that patients with high expression of COL10A1 have an open tight junction signaling pathway, which is closely related to EMT." (PMID 39247832, 2024). "It was possible to treat the protein level regarding COL10A1 in serum as a biomarker for diagnosing tumor prognosis in early stage, thereby identifying colorectal cancer and adenoma." (PMID 36276283, 2022). "Up-regulation of COL10A1, a molecular marker of early colorectal cancer, encouraged colorectal cancer cell proliferation, migration, and invasion." (PMID 36246404, 2022). "As revealed by biological functional experiments, COL10A1 overexpression strengthened colorectal cancer cells in terms of the proliferation, the migration, and the invasion, and COL10A1 knockdown hindered the tumorigenesis in vivo." (PMID 36276283, 2022). "Collectively all these results reveal that the COL11A1 gene has a positive association and correlation with THBS2, COL10A1, COL5A2, and COL1A2 to upregulate the gene expression to induce the development of colorectal cancer." (PMID 33597969, 2021). "Meanwhile, it was independently reported in colorectal cancer, lung cancer and oral cancer, and the expression of COL10A1 gene in tumor tissue was higher than that in normal corresponding tissue." (PMID 33371777, 2021). "Studies in gastric and colorectal cancer have shown that high expression of COL10A1 promotes epithelial‐mesenchymal transformation and tumor cell invasiveness and is associated with poor prognosis." (PMID 33934516, 2021). "In addition, colorectal cancer patients with high COL10A1 expression presented a poorer prognosis than those with low expression." (PMID 37974070, 2023). "Collagen type X alpha 1 chain (COL10A1) encoded by COL10A1 gene is a member of the collagen family, whose activity was associated with promotion of metastasis through epithelial-mesenchymal transition and poor survival in gastric and colorectal cancer." (PMID 36675137, 2023). "Moreover, the expression level of COL10A1 in colorectal cancer predicts metastatic and immunogenic properties." (PMID 37974070, 2023). "Furthermore, COL10A1 expression was found to be abnormally elevated in colorectal cancer vs. normal controls and inversely correlated with the outcome of colorectal cancer patients." (PMID 37974070, 2023). "In addition, serum protein concentrations regarding COL10A1 exhibited an obvious increase in adenomas and colorectal cancer cases relative to the control samples." (PMID 36276283, 2022). "Collectively all these experimental data clearly reveal that the COL11A1 gene along with its associated THBS2, COL10A1, COL5A2, and COL1A2 might serve as a prognostic biomarker for colorectal cancer." (PMID 33597969, 2021). "In addition, COL10A1 has also been studied in lung adenocarcinoma and colorectal cancer." (PMID 38063927, 2023).
colorectal cancer (continued). "Co-IP experiments indicated that VSNL1 can bind to COL10A1, which, when up-regulated, can promote colorectal cell proliferation, migration and invasion and reverse the effect of sh-VSNL1 on colorectal cancer cells." (PMID 38909013, 2024). "A previous pan-cancer single cell analysis of ovarian, lung, and colorectal cancer, showed that COMP, COL10A1, COL11A1, and MMP1 all have higher expression in CAFs26." (PMID 34732773, 2021). "The PathwayMapper tab in cBioPortal servers shows the alteration frequency of COL11A1, THBS2, COL10A1, COL5A2, and COL1A2 over the various pathways on the colorectal cancer dataset using a white to red color scale where the more frequently altering gene shows greater intensity of the red color." (PMID 33597969, 2021).
osteoarthritis (17 papers, 2011 to 2026). A noninflammatory degenerative joint disease occurring chiefly in older persons, characterized by degeneration of the articular cartilage, hypertrophy of bone at the margins and changes in the synovial membrane. "TGF‐β can promote angiogenesis, infiltrate subchondral bone, exacerbate osteoarthritis progression, and increase the expression of terminal differentiation genes such as Mmp13, Runx2, and Col10a1." (PMID 40837199, 2025). "Here, we investigate the role of miR-101a in chondrocyte hypertrophy and osteoarthritis (OA) progression, focusing on its regulation of Col10a1 expression." (PMID 41674655, 2025). "The analysis revealed a notable upregulation of key osteoarthritis markers, such as COL10A1, MMP13, and SPP1, along with downregulating chondrogenic markers, including ACAN, COL1A2, COL2A1, and SOX9." (PMID 39337501, 2024). "RNA sequencing unveiled significant transcriptome changes during the 7-day SMG culture, including the notable upregulation of key osteoarthritis markers such as COL10A1, MMP13, and SPP1, along with pathways related to inflammation and calcification." (PMID 38907358, 2024). "Further delineation of these elements/factors has the potential to identify novel therapeutic targets for multiple skeletal disorders, including osteoarthritis, that show abnormal Col10a1 expression and altered chondrocyte maturation." (PMID 21887706, 2011). "Abnormal Col10a1 expression is a well-established feature in osteoarthritis." (PMID 38144567, 2023). "HIF-2α is involved in a pathway that promotes osteoarthritis degradation and regulates the expression of genes related to chondrocyte hypertrophy and differentiation, such as COL10A1 and RUNX2, and the expression of genes related to ECM degradation, such as MMP9, MMP13, MMP3, ADAMTS." (PMID 36503684, 2022). "Previous report has shown that increased MMP-1, MMP-3, MMP-9, MMP-12, and MMP-13, VEGF-A, and COL10A1, triggered by hypoxia-inducible factor (HIF)-2, play a vital role during osteoarthritis development." (PMID 31766662, 2019). "COL10A1 is a well-known marker of chondrocyte hypertrophy, while VEGF induces angiogenesis and characteristic events of the degradation of articular cartilage in pathologies such as osteoarthritis." (PMID 38666953, 2024).